PVT1 (Pvt1 oncogene)
Diseases named in the same sentence as PVT1 in open-access papers (continued):
Sharing a sentence is not in itself a finding about the gene and the disease.
rhabdomyosarcoma (1 paper, 2022). A rare aggressive malignant mesenchymal neoplasm arising from skeletal muscle. "The remaining four DElncRNAs (MEG3, maternally expressed gene 3; RMST, rhabdomyosarcoma 2-associated transcript; HNF1A-AS1, HNF1A antisense RNA 1; and PVT1, and plasmacytoma variant translocation 1) and two DEmiRNAs (hsa-mir-429 and hsa-mir-200a) appeared to be protective." (PMID 36101743, 2022).
sarcoidosis (1 paper, 2024). Sarcoidosis is a multisystemic disorder of unknown cause characterized by the formation of immune granulomas in involved organs. "Sarcoidosis associated pulmonary fibrosis has some unique features such as variants of annexin A11 and PVT1." (PMID 39281278, 2024). "Also, SNPs variants of PVT1 (plasmacytoma variant translocation 1) gene were associated with increased susceptibility to fibrosis in group of patients of African American descent with sarcoidosis." (PMID 39281278, 2024).
serous ovarian cancers (1 paper, 2022). "Among all cancers within the TCGA Firehose Legacy studies, serous ovarian cancer exhibited the highest frequency of alterations in PVT1 (43%)." (PMID 35820706, 2022).
thymoma (1 paper, 2017). A neoplasm arising from the epithelial cells of the thymus. "Because of PVT1 detected in only two normal tissues of thymoma patients, PVT1 sequencing data of 21 types were chose to analyze the differential expression between cancers and corresponding normal tissues." (PMID 29088881, 2017).
thyroid nodule (1 paper, 2021). A small circumscribed mass in the THYROID GLAND that can be of neoplastic growth or non-neoplastic abnormality. "The expressions of MALAT1, HOTAIR, PVT1 and the cytological class of a cohort of n = 34 thyroid nodules have been used to fit kernel distributions with Epanechnikov bases functions and positive support to determine the likelihoods p(MALAT1|tum)." (PMID 33030666, 2021). "Next, analysis of suspicious thyroid nodules versus the contra-lateral tissue revealed that expression of MALAT1, HOTAIR, PVT1, and NEAT1 was significantly higher in malignant lesion than in contra-lateral normal tissue (P < 0.05)." (PMID 33030666, 2021). "Hence, each thyroid nodule has been classified as malignant if the probability p(mal.|MALAT1,HOTAIR,PVT1,cyt)." (PMID 33030666, 2021).
tongue squamous cell carcinoma (1 paper, 2022). A squamous cell carcinoma that arises from the tongue. "The β-catenin/GSK3β signaling can be inactivated via downregulating the H19 lncRNA in tongue squamous cell carcinoma (TSCC) cells or through overexpressing the PVT1 (plasmacytoma variant translocation 1) lncRNA in OSCC and HNSCC cells." (PMID 36106022, 2022).
ZIKV infection (1 paper, 2017). "Moreover, PVT1, inhibitor of cell proliferation, is upregulated by ZIKV infection, and therefore could participate in virus-induced cell cycle dysregulation." (PMID 29116029, 2017). "Thus, the upregulation of PVT1 could play a role in the disrupted cell cycle due to ZIKV infection." (PMID 29116029, 2017).
cancer (476 papers, 2009 to 2026). A tumor composed of atypical neoplastic, often pleomorphic cells that invade other tissues. "Consistent with this conclusion, cancer genome sequencing identified recurrent mutations encompassing the PVT1 promoter." (PMID 40743223, 2025). "This acts as a double-edged sword where bivalency and ME are advantageous in early development but make Pvt1 more susceptible to methylation in adult cancers." (PMID 41223055, 2025). "Plasmacytoma variant translocation 1 (PVT1) has been identified as an oncogenic lncRNA implicated in multiple cancers." (PMID 40904706, 2025). "Correlation analysis showed that PVT1 was associated with several pathways related to cancer progression, and MYC targets showed the strongest positive association." (PMID 39376555, 2024). "A prominent example of a lncRNA in the context of cancer biology is the Plasmacytoma Variant Translocation 1 (PVT1)." (PMID 38731892, 2024). "The PVT1 gene has been identified as an oncogene encoding PVT1 long noncoding RNA, and increased expression of PVT1 has been found to be associated with numerous cancer types." (PMID 39061962, 2024). "For instance, the PVT1 locus frequently hosts mutations in patients with various forms of cancer, adding a layer of genetic predisposition in the regulatory role of lncRNA loci in complex disease." (PMID 39123456, 2024). "PVT1 gene is located on the chromosomal locus 8q24.21, a region frequently associated with copy number amplification in various cancer types." (PMID 38287522, 2024). "The PVT1 transcript participates in cell cycle regulation, associates with pancreatic neoplasms, and is overall considered a suitable biomarker for cancer." (PMID 39123456, 2024). "The oncogenic role of the plasmacytoma variant translocation 1 gene (PVT1), a lncRNA located at 8q24.21, has been established in various cancers." (PMID 39160596, 2024). "The long non-coding RNA (lncRNA) plasmacytoma variant translocation 1 (PVT1) plays an oncogenic role in multiple cancers due to its high expression." (PMID 36944636, 2023). "LncPVT1 and CircPVT1 are isoforms for the PVT1 gene and are associated with cancer progression and carcinogenesis." (PMID 37573419, 2023). "In most human cancers, including MM, lncRNA plasmacytoma variant translocation 1 (PVT1) corresponds with c-Myc." (PMID 37987364, 2023). "An increasing number of studies have found that long noncoding RNA plasmacytoma variant translocation 1 (PVT1) plays an important role in cancer development." (PMID 36195846, 2022). "The plasmacytoma variant translocation 1 (PVT1) is a long non-coding RNA gene involved in human disease, mainly in cancer onset/progression." (PMID 34754096, 2022). "The lncRNA human plasmacytoma variant translocation 1 (PVT1) is an oncogenic lncRNA that has been reported to be involved in cancer progression and chemoresistance; however, mechanisms underlying its regulation in PC are not yet clear." (PMID 36558998, 2022). "Because PVT1 functions as an oncogenic molecule in various cancers, TMPO-AS1 was chosen as the miR-140/miR-143-associated lncRNA in our study." (PMID 35712514, 2022). "The location of lncRNA PVT1 is thought to be a cancer risk locus shared with the well-known MYC oncogene." (PMID 36118202, 2022). "The circRNA molecule originates from the PVT1 locus that encodes a lncRNA called lncPVT1, a well-known long non-coding RNA involved in cancer development and progression." (PMID 35090471, 2022). "Great interest has recently been devoted to the “plasmacytoma variant translocation 1” (PVT1) lncRNA gene, which produces both linear and circular transcripts that have been reported to be overexpressed in several cancer types." (PMID 34754096, 2022). "Long non-coding RNA (lncRNA) plasmacytoma variant translocation 1 gene (PVT1) is related to the progress of various cancers." (PMID 35152842, 2022).
cancer (continued). "In human cancers mutations present in the PVT1 promoter alter the tridimensional structure of the TAD and allow the enhancers to promote c-MYC transcription favoring tumor progression." (PMID 35090471, 2022). "The plasmacytoma variant translocation 1 (PVT1) gene, located on human chromosome 8q24, was the first LncRNA found in human cancer." (PMID 35241975, 2022). "Previous studies in the association between PVT1 polymorphisms and diseases were only reported in the field of cancer and kidney disease." (PMID 35036445, 2022). "Several studies have highlighted the role of the lncRNA plasmacytoma variant translocation 1 (PVT1) in cancer and cardiovascular disease." (PMID 35328496, 2022). "PVT1 is closely associated with the onset, development, invasion, migration, and treatment of cancer." (PMID 36195846, 2022). "PVT1 is highly expressed in various types of cancer, the expression level of PVT1 is commonly associated with the hypoxia process." (PMID 35256612, 2022). "This evidence is striking because it underlines the dual behaviour of PVT1 in cancer, either as an oncogene or as a tumour suppressor gene." (PMID 34754096, 2022). "lncRNA PVT1 is located in the chr8q24.21 region where there are targets with the highest DNA copy numbers in cancer cells, indicating a high risk of cancer." (PMID 35038974, 2022). "Plasmacytoma variant translocation 1 (PVT1) is a common lncRNA located in a cancer-related region chr8q24.21 region, consisting of 1716 nucleotides." (PMID 36147488, 2022). "The human PVT1 gene is located on chromosome 8q24 and encodes a lncRNA, which is involved in a variety of cancer types and plays a major role in cancer development and metastasis." (PMID 35433465, 2022). "The expression levels of lncRNA plasmacytoma variant translocation 1 (Pvt1), previously reported as a cell cycle regulator in carcinoma, were shown to increase under each muscle atrophy condition in mice." (PMID 35892588, 2022). "PVT1 exon 9 was also found to induce the formation of malignant tumors in mice, a phenotype that strongly suggests an association with aggressive forms of PCa." (PMID 33796469, 2021). "Plasmacytoma variant translocation 1 (PVT1) is a long non-coding RNA (lncRNA) that functions as an oncogene in many cancers and is known to promote MYC expression in I-BET151-resistant AML cells in a BRD4-independent manner." (PMID 34540687, 2021). "The oncogenic lncRNA Plasmacytoma variant translocation 1 (PVT1) acts as a miRNA sponge in several cancers, leading to enhanced proliferation and metastasis." (PMID 34439196, 2021). "There are many studies on the role of the lncRNA plasmacytoma variant translocation 1 (PVT1) in cancer." (PMID 34898354, 2021). "Circular RNA PVT1 (circPVT1), derived from the known cancer susceptibility locus PVT1 exon-3, in chromosome 8q24, is an oncogenic noncoding RNA with emerging clinical importance." (PMID 33728345, 2021). "CircPVT1 is derived from a long noncoding RNA region of oncogene PVT1, which is a cancer susceptibility locus." (PMID 34966683, 2021). "Due to the increasing evidence of PVT1-encoded miRNAs in cancer, we were interested in elucidating the role of miR-1205 in cancer." (PMID 34386489, 2021). "Plasmacytoma variant translocation 1 (PVT1) is a newly discovered long non-coding RNA which preforms regulating functions as an oncogenic molecule in different cancers." (PMID 35127729, 2021). "Long non-coding RNA plasmacytoma variant translocation 1 gene (PVT1) was proved to be associated with the development of diverse human cancers, including CC." (PMID 33817293, 2021). "Another study has also shown that upregulation of both lncRNA PVT1 and circPVT1 is associated with poor survival in patients with different cancers." (PMID 33793089, 2021). "PVT1 is upregulated in various carcinomas, and its overexpression is associated with poor survival in patients." (PMID 34288803, 2021).
cancer (continued). "Identifying and understanding the variety of activities of PVT1 involved in cancers is a necessity for the development of PVT1 as a diagnostic biomarker or therapeutic target in cancers where PVT1 is dysregulated." (PMID 32117705, 2020). "Among these studied lncRNAs, lncRNA plasmacytoma variant translocation 1 (PVT1) is one of the most well-documented cancer-associated regulators in several cancer types." (PMID 32499447, 2020). "PVT1 is a novel lncRNA encoded by the human PVT1 gene with oncogenic roles in numerous human cancers that has been widely studied." (PMID 32249459, 2020). "Plasmacytoma variant translocation 1 (PVT1) is a lncRNA that has been found to serve an oncogenic role in a variety of malignant tumors." (PMID 31320749, 2020). "Plasmacytoma variant translocation 1 (PVT1), a long non-coding RNA encoded by the human PVT1 gene, is located in the well-known cancer-related region, 8q24." (PMID 32117705, 2020). "PVT1 has been shown to be an activator of c-Myc transcription, and likewise, c-Myc has also been implicated as a PVT1 activator in cancer cells." (PMID 32117705, 2020). "The non-protein coding gene locus plasmacytoma variant translocation 1 (PVT1) is located at human chromosome 8q24 and is dysregulated in several cancers." (PMID 32358016, 2020). "PVT1 is a lncRNA amplified in human cancers, particularly in gastrointestinal tumors, and associated with poor prognosis." (PMID 33291485, 2020). "LncRNA Plasmacytoma Variant Translocation 1 (PVT1), was well known to play a part in tumorigenesis in multiple cancer types." (PMID 32624708, 2020). "Dozens of further cancer-associated PVT-1 translocation events have been documented, underpinning the reported roles of this lncRNA in oncogenesis (section Amplifications and Deletions)." (PMID 33329688, 2020). "As a potential tumor biomarker, plasmacytoma variant translocation 1 gene (PVT1) is involved in the development and progression of multifarious cancers." (PMID 33188158, 2020). "PVT1 (plasmacytoma variant translocation 1) lncRNA is located on chromosomal 8q24.21, a large locus frequently amplified in human cancers and predictive of increased cancer risk in genome-wide association studies (GWAS)." (PMID 32083000, 2020). "Plasmacytoma variant translocation 1 (PVT1) is another lncRNA that exerts its oncogenic effects by stabilizing the c-Myc protein in cancer." (PMID 32164715, 2020). "This list contained genes previously associated with co-amplification with cMYC in cancer, such as PVT1 or FAM84B, thus validating our strategy." (PMID 32932846, 2020). "For example, PVT1 (plasmacytoma variant translocation 1) is a well-known lncRNA that is amplified or overexpressed in cancer." (PMID 32503290, 2020). "Numerous studies have confirmed that PVT1 upregulation is associated with tumor progression and reduced survival in several types of cancer." (PMID 31766781, 2019). "The plasmacytoma variant translocation 1 (PVT1) gene located on chromosome 8q24 is among the top targets of copy number alteration in cancer." (PMID 31205469, 2019). "Here we present a review of recent literature examining the contribution of ncRNAs encoded by the PVT1 locus and their associated ceRNA networks to the development of resistance to common chemotherapeutic agents used to treat human cancers." (PMID 31508377, 2019). "Plasmacytoma variant translocation 1 (PVT1) is a novel lncRNA that is upregulated in various human cancers." (PMID 30931332, 2019). "PVT1 is a lncRNA with oncogenic function in multiple cancers and it maps on chromosome 8q24, a recognized cancer risk region that is shared with the well-known MYC oncogene." (PMID 31581735, 2019). "In humans, increased copy number and overexpression of lncRNA PVT1 are tightly associated with a variety of cancer types, including hepatocellular carcinoma, gastric cancer, esophageal cancer, cervical cancer, bladder cancer and acute myeloid leukemia." (PMID 30925926, 2019).
cancer (continued). "These factors are well-characterized in cancer, and their association with PVT1 has the potential to provide major insights into its role in tumorigenesis." (PMID 31249809, 2019). "Although the mechanism underlying lncRNA Pvt1 activity in cancer cells has been elaborated in detail, how lncRNA Pvt1 regulates MDSC function and differentiation has not been elucidated to date." (PMID 30925926, 2019). "LncRNA plasmacytoma variant translocation 1 (PVT1) is a newly discovered oncogenic factor that has been confirmed to be overexpressed in many cancer cells." (PMID 31380270, 2019). "Plasmacytoma variant translocation 1 (PVT1) is a well-established oncogene in OC, as well as other cancers such as gastric and breast." (PMID 32039022, 2019). "At the chromosomal level, PVT1 is easily fused with other genes to form a fusion gene that drives the abnormal expression of cancer-associated proteins." (PMID 31309249, 2019). "In general, PVT1 expression was significantly associated with metastasis, clinical stage, and poor prognosis in various types of cancer in different systems." (PMID 30083911, 2019). "In recent years, some studies have shown that PVT1 is closely associated with clinicopathological features and can act as a prognostic biomarker in cancer." (PMID 31497532, 2019). "The PVT1 promoter is a target of genetic mutations and chromosomal rearrangements in various forms of cancer, further highlighting its regulatory importance." (PMID 31658672, 2019). "Because lncRNA PVT1 plays a vital role in cancer, studies on the underlying mechanisms suggest promising clinical applications." (PMID 31497532, 2019). "The long noncoding RNA plasmacytoma variant translocation 1 (lncRNA Pvt1) is a potential oncogene in a variety of cancer types." (PMID 30925926, 2019). "It contains a large number of risk alleles that are implicated in cancer, including the lncRNA Plasmacytoma Variant Translocation 1 (PVT1) as well as an associated protein-coding gene MYC." (PMID 31249809, 2019). "For example, the common candidate driver lncRNA PVT1 was associated with the hallmark ‘Genome Instability and Mutation’ in three cancer types (OV, LUAD and HNSC)." (PMID 30216655, 2018). "These splice variants either compete with PVT1 for miRNA binding or affect its ceRNA activity, due to their differential expression levels between normal and cancer states." (PMID 29702599, 2018). "Studies in other cancers have shown that disease-specific risk loci at 8q24.21 lie within tissue-specific enhancers interacting with MYC or PVT1 promotors." (PMID 29632299, 2018). "PVT1 is among those long non-coding RNAs, which is overexpressed and associated with tumorigenesis and poor prognosis in a range of cancers." (PMID 29254209, 2017). "Plasmacytoma variant translocation 1 (PVT1) has recently been reported to be aberrantly expressed and serves as a prognostic biomarker in many types of cancers." (PMID 29348896, 2017). "Fourth, there were few studies on association of serum PVT1 expression with cancer diagnosis / detection, some of our significant findings was limited by the low precision as indicated by the wide confidence intervals." (PMID 29088881, 2017). "As a result, it is important to combine these published data by meta-analysis and evaluate the association between PVT1 expression and prognosis as well as clinicopathological characteristics in cancer patients." (PMID 29348896, 2017). "Because of the tissues derived from different organs, the diagnostic effects of PVT1 were also tested in the same organ cancers." (PMID 29088881, 2017). "The long non-coding RNA (lncRNA) plasmacytoma variant translocation 1 (PVT1) is overexpressed in several malignant tumors, including BC." (PMID 28969069, 2017). "PVT1 is overexpressed, inhibits apoptosis, and is associated with tumorigenesis and poor prognosis in many cancers." (PMID 29254209, 2017).